ATF1 (activating transcription factor 1)
Diseases named in the same sentence as ATF1 in open-access papers (continued):
Sharing a sentence is not in itself a finding about the gene and the disease.
tumor (55 papers, 2008 to 2025). "In a Mitf loss-of-function mutational background, Ewsr1::Atf1 mouse tumor formation was slightly delayed." (PMID 38916046, 2024). "In human epidermoid tumor cells, dominant negative mutation ATF1 reduces the transcription expression of H-2DD gene." (PMID 35397606, 2022). "The two tumours that presented a BRAF or NRAS mutation also presented the ATF1-EWS fusion gene and were considered atypical." (PMID 22693489, 2012). "ATF1, a reported tumor suppressor, carried a splice variant in all samples." (PMID 37810779, 2023). "Ultimately, three patients died of disease, all of whom underwent a subtotal resection for an EWSR1::ATF1 fusion-positive tumor." (PMID 38291529, 2024). "Among the 74 IMT cases reported to date, three patients eventually died of disease, all of whom underwent a STR for an EWSR1::ATF1 fused tumor." (PMID 38291529, 2024). "Recently, a group of intra-abdominal FET(EWSR1/FUS)::CREB(CREM/ATF1) fused unclassified neoplasms has been reported followed by recent recognition of an analogous extra-abdominal category of unclassified neoplasms carrying EWSR1::ATF1 fusions." (PMID 39249507, 2024). "Ubiquitous EWSR1::ATF1 induction by either TAT-Cre or tamoxifen (for CreER) injection resulted in tumor formation and additional developmental deformities." (PMID 38916046, 2024). "Here, we review our current knowledge of human malignancies carrying the specific subset of EWSR1 rearrangements that leads to the expression of the EWSR1::ATF1 tumor-driver chimeric protein." (PMID 39769457, 2024). "Evaluation of the clinical outcome of these patients revealed STR, younger age (< 14 years old), infratentorial location, and possible EWSR1::ATF1 fusion as poor prognostic factors for this recently defined tumor type." (PMID 38291529, 2024). "In comparison to two control sgRNAs targeting nonessential genes Rosa26 and H11, two independent sgRNAs targeting Mc1r blocked α-MSH-induced CREB1/ATF1 phosphorylation and slowed tumor growth." (PMID 37714844, 2023). "In MM for example, gain in ATF1 and SOX10, associated with loss of TFAP2A expression, drive tumor growth and metastasis by regulating, in an opposing manner, a number of genes involved in cell adhesion, extracellular matrix remodeling, and cell survival." (PMID 35477713, 2022). "ATF1 is overexpressed in esophageal squamous cell carcinoma and positively correlated with lymph node metastasis and early tumor invasion." (PMID 35397606, 2022). "We examined the tumor for EWSR1/ATF1 transcripts using RT-PCR and direct sequencing on the paraffin-embedded tissue." (PMID 33478436, 2021). "We observed suppressed E-cadherin expression and decreased CREB/ATF-1 phosphorylation in MUC2-silenced tumor cells after rIL-6 treatment." (PMID 28725043, 2017). "The results of xenograft experiments showed that overexpression of ATF1 in CNE1 cells (CNE1:ATF1) led to markedly increased tumor formation compared with the control CNE1 cells." (PMID 28032861, 2016). "The two tumours which were found to harbor mutations in the BRAF and NRAS gene also presented the ATF1-EWS fusion gene and were considered atypical." (PMID 22693489, 2012). "Differences in molecular fusion type (EWSR1/CREB1 versus EWSR1/ATF1), tumour burden at relapse, and prior treatments may partly explain the variability in responses across cases." (PMID 41020828, 2025). "One tumor each had an EWSR1::ATF1 (8%) and EWSR1::PBX3 (8%) fusion." (PMID 40748380, 2025). "Given the lethality of EWSR1::ATF1 in multiple lineages, it may be worthwhile to investigate methods to promote oncogene-induced senescence and drive the tumor into an unstable and apoptotic state." (PMID 38916046, 2024). "This domain configuration fueled the idea that EWSR1::ATF1 chimeras act like aberrant transcription factors, which dysregulate the gene expression pattern of host cells, leading to unleashed proliferation and, thus, tumor formation." (PMID 39769457, 2024).
tumor (continued). "Whether these gonadal neoplasms are part of the EWSR1/FUS::ATF1/CREM fusion-driven tumor spectrum with subtle organ-specific phenotypic differences remains controversial." (PMID 39031200, 2024). "Furthermore, 10 of these 26 (38.5%) patients had a tumor with an EWSR1::ATF1 fusion, eight (30.8%) had EWSR1::CREB1 fusion, six (23.1%) had EWSR1::CREM, one (3.8%) had EWSR1::CREB3L3, and one (3.8%) had FUS::CREM fusion." (PMID 38291529, 2024). "Besides EOR, age, and EWSR1::ATF1 fusion, we further identified another novel prognostic factor: tumor location." (PMID 38291529, 2024). "ATF1 plays a key role in tumour progression in a tumour‐specific manner." (PMID 33342045, 2021). "The tumor was found to be positive for the EWSR1/ATF1 fusion gene." (PMID 33478436, 2021). "Importantly, simultaneous knockdown of Pin1 and overexpression of ATF1 in CNE1 cells (CNE1:ATF1/shPin1) led to tumor formation much slower than overexpression of ATF1 in CNE1 cells (CNE1:ATF1)." (PMID 28032861, 2016). "Furthermore, the newly identified phosphorylation of ATF1 at Thr184 was suggested to have an important role in ATF1 function of transcription and tumor promotion." (PMID 28032861, 2016). "We also assessed whether bortezomib can neutralize the suppression of T cell cytolytic molecule expression mediated in the tumor microenvironment by the immunosuppressive cytokine TGFβ via the Smad-ATF1 pathway." (PMID 26431276, 2015). "Indeed we have shown that out of the endothelial enriched genes, Smurf2, Hex-B, Atf1, and Nras, plus Rrm2, which has known roles in tumour biology, that depletion of Rrm2, Atf1 and Hex-B have anti-angiogenic consequences in ex vivo mouse aortic ring assays." (PMID 23056178, 2012). "However, the role of phosphorylated ATF1 at Thr184 in tumor is still unclear." (PMID 35397606, 2022). "We further explored if rs1129406 (ATF1, 12q13), rs12303082 (FAM186A, 12q13), rs6580742 (FAM186A, 12q13), rs16888728 (UTP23, 8q24) and rs3184504 (SH2B3, 12q24) genotypes affect the CRC risk differentially by sex, age at diagnosis, tumor site, stage and MSI status." (PMID 26553438, 2015). "Among 12 tumors with known fusion partners, the fusions partner was CREB1 in 6 cases (50%), CREM in 4 tumors (33%), ATF1 in one tumor (8%) and PBX3 (8%) in another tumor." (PMID 40748380, 2025). "Similarly, the absence of codons 65 to 109 of ATF1 in some EWSR1::ATF1 fusion products, apparently, excludes the putative activation domain of ATF1, raising the question of if the differential activity and, consequently, tumor specificity of these variants correlates to the tumor phenotype." (PMID 39769457, 2024). "Median tumor size was 3.6 cm (0.3–11.1 cm), and 24/26 (94%) tissues analyzed at our institute were EWSR1::ATF1-translocation-positive." (PMID 39535601, 2024). "We herein describe 4 unclassified extra-abdominal soft tissue (n = 3) and bone (n = 1) neoplasms displaying epithelioid and round cell morphology and carrying an EWSR1::ATF1 fusion." (PMID 39031200, 2024). "Subsequently, split signals of EWSR1, ATF1 and CREB1 in tumor cells of the large lesion were 5%, 2% and 0%, respectively." (PMID 32803839, 2020). "To detect the presence of EWSR1, ATF1 and CREB1, we counted 100 nuclei in tumor cells and that showed a pair of fused and split signals, and calculated the percentage of split signals." (PMID 32803839, 2020). "Two patients with EWSR1::ATF1 fusion experienced recurrence or metastasis during the follow-up period, of which one died of the tumor, and two had no recurrence or metastasis during the follow-up period." (PMID 41341384, 2025). "Activating Myc resulted in more rapid Ewsr1::Atf1 tumor development, although these tumors did not histologically recapitulate CCS." (PMID 38916046, 2024). "Our data suggested that lack of correlation between ATF1 rs11169571 and clinicopathological parameters including age, gender, primary tumor extension, lymph node status, and metastasis in patients." (PMID 30905073, 2019).
tumor (continued). "A FISH was performed on formalin-fixed paraffin-embedded tumour tissues and found a translocation of EWSR1, which was confirmed by the next-generation sequencing (NextSeq 550 System, illumina) and correspond to the fusion transcript EWSR1/ATF1." (PMID 31350293, 2019). "The comprehensive list of target tumor-driver genes of EWSR1::ATF1 is not known." (PMID 39769457, 2024). "As a non-fusion protein molecule, ATF1 also plays an important role in tumor development." (PMID 35397606, 2022). "A similar analysis with combined ATF‐1 data sets revealed the ability of AR‐42, but not GTx‐024 treatment, to significantly impact ATF‐1 target gene regulation in tumor‐bearing mice implicating AR‐42's ability to modulate ATF‐1 activation in its anti‐cachectic efficacy." (PMID 31930715, 2020). "However, the mRNA expression of ATF1 was not higher in NPC compared with non-tumor tissues using the GEO data." (PMID 28032861, 2016).
cancer (40 papers, 2014 to 2025). A tumor composed of atypical neoplastic, often pleomorphic cells that invade other tissues. "Analysis of ATF1 co-expressed genes in pan-cancer TCGA dataset confirms that genes associated with mitochondrial function are among the top ATF1 co-expressed genes." (PMID 37463926, 2023). "In summary, coupled activation of nuclear pluripotency and mitochondrial biogenesis, directed by TME neural signal-ATF1 pathway serves as a conserved mechanism underlying cancer stem-like state." (PMID 37463926, 2023). "Combined mitochondrial and nuclear targets of ATF1/CREB1 is associated with worse prognosis in cancer patients from the TCGA and GEO datasets compared with either mitochondrial or nuclear subset of targets." (PMID 37463926, 2023). "In addition, ATF1 deficiency impairs the sphere formation in cancer cells derived from xenografts, whereas cell proliferation is modestly affected." (PMID 37463926, 2023). "However, few studies analyzed the genetic variants in ATF1 and risk of cancer." (PMID 30905073, 2019). "Interestingly, when considering TA in the presence of family history of cancer, positive association was found for carriers of a TT genotype (thus two copies of the minor allele T) in ATF1 rs11169552 (P = 0.00004), and for carriers of a GG genotype in DUSP10 rs6687758 (P = 0.003)." (PMID 29445242, 2018). "The shRNAs targeting ATF1 and CREB1 are consistently decreased in MDA-MB-231, NCI-H460 and DLD1 spheres, indicating impaired cancer stemness in ATF1/CREB1 deficient cells." (PMID 37463926, 2023). "Collectively, the data establish ATF1 as a specific CRE transcription factor that dictates TME neural signals to enable cancer stemness." (PMID 37463926, 2023). "Collectively, these data suggest that deficient mitochondrial biogenesis induces dysfunctional mitochondria to impair cancer stemness in ATF1 depleted cells." (PMID 37463926, 2023). "In summary, this study reveals a novel mechanism of cancer stemness triggered by the neural signal-ATF1 dependent coordination of nuclear pluripotency and mitochondrial biogenesis." (PMID 37463926, 2023). "Results from gel shift and supershift assays, Southwestern blotting studies, and gel shift and supershift assays suggest that the 27-bp GSN cis-element is preferentially bindable by activating transcription factor 1 (ATF1) in cancer cells." (PMID 37970212, 2023). "In agreement, cancer stemness indicated by both sphere-forming capacity and ALDH activity are partially rescued by MitoTempo and MitoQ in ATF1 deficient cells." (PMID 37463926, 2023). "We next determined how nuclear pluripotency and mitochondrial biogenesis contribute to ATF1 mediated cancer stemness." (PMID 37463926, 2023). "The results indicate that ATF1 depletion leads to senescence-like phenotype in stem-like cancer cells." (PMID 37463926, 2023). "To determine the clinical relevance of ATF1 in coordinating nuclear pluripotent and mitochondrial regulators in cancer, we evaluated the correlations between ATF1 and candidate genes in the TCGA dataset." (PMID 37463926, 2023). "Oncogenes ATF1 and HOXA11, and HNF4G have been implicated in multiple cancers and are involved in the positive regulation of the RNA metabolic process." (PMID 35008416, 2022). "The experimental results showed that MMP2 mRNA expression levels were positively correlated with ATF1 in cancer cells except BGC823 cells (R2 = 0.975, P = 0.002)." (PMID 35397606, 2022). "CREB/ATF1 activation antagonized the anti-cancer effects of aspirin, and pharmacological targeting of CREB/ATF1 significantly enhanced the efficacy of aspirin against HCC cancer cells." (PMID 35269900, 2022). "Cyclin D1 is one of CREB/ATF1 and wnt/β-catenin targets and a critical driver of cancer cell proliferation." (PMID 33917483, 2021). "According to the present literatures, the major function of CDK3 is a promoter for cancer cell growth and transformation by phosphorylating its substrates, such as ATF1, c-Jun, NFAT3 and IK3-1/Cables." (PMID 29156693, 2017).
cancer (continued). "Our experiments showed that IL-6 treatment induced STAT3 and Chk2 activation and attenuated CREB/ATF-1 phosphorylation in MUC2-silenced HT-29 cancer cells." (PMID 28725043, 2017). "In other cancer cell lines HepG2 and A549, ATF1 transcriptional activation of Bcl-2 was also impaired by knockdown of Pin1." (PMID 28032861, 2016). "Quantification of a mitochondrial gene panel confirmed that MYC restores the majority of mitochondrial genes in ATF1 deficient MDA-MB-231 and A549 cells, indicating that coordinated nuclear pluripotency and mitochondrial biogenesis are required for ATF1 dependent cancer stemness." (PMID 37463926, 2023). "ATF1 integrates adrenergic signal and cell-intrinsic stemness factors by simultaneously coordinated trans-activation of genes involved in both nuclear pluripotency and mitochondrial rejuvenation, thereby driving cancer cells into stem-like state." (PMID 37463926, 2023). "Upon activation by norepinephrine, ATF1 potentiates cancer stemness by coordinated trans-activation of both nuclear pluripotency factors MYC/NANOG and mitochondrial biogenesis regulators NRF1/TFAM, thereby orchestrating nuclear reprograming and mitochondrial rejuvenating." (PMID 37463926, 2023). "Importantly, downregulation of CPS1 leads to an increase in the levels of cyclic AMP (cAMP) and activation of protein kinase A (PKA)-cAMP response element-binding protein (CREB)/ATF1 axis, which compromises the anti-cancer effects of aspirin." (PMID 33917483, 2021). "Finally, we tried to alter the cancer cell fate by modulating the cell-type-specific binding pattern of EWS/ATF1." (PMID 31488818, 2019). "Our previous study indicates that ATF1 plays a pro‐cancer role in NPC." (PMID 30905073, 2019). "ATF1 also promotes FRA-1 expression by binding to the ATF site on the FRA-1 promoter, thereby enhancing the response of cancer cells to mitogens." (PMID 40746611, 2025). "Chromosome translocations between ATF1 and RNA-binding proteins like FUS or EWSR1 have been reported to form chimeric proteins that lead to cancer (36, –, 38)." (PMID 40607797, 2025). "Glabridin inhibits cancer cell proliferation and survival by downregulating cyclin D3, CDK2, and CDK4, blocking the G1/S phase transition, and reducing CREB and ATF1 phosphorylation." (PMID 39723390, 2024). "In parallel, the transcription factor activity related to pro-metastatic response (SMAD1,2,3 and HNF1a) and cancer cell maintenance (OCT4, and ATF1) was similarly increased at 4 h and remained pronounced through the 8 h time point following CM incubation." (PMID 38398186, 2024). "Thirdly, we have characterized ATF1 as a core CRE transcription factor mediating the crosstalk between TME neural signaling and cancer stemness." (PMID 37463926, 2023). "In accordance, ATF1 is positively correlated with both pluripotent (33/33, 23/33 of cancer types for MYC and NANOG, respectively) and mitochondrial regulators (33/33 of cancer types for both TFAM and NRF1) in TCGA cohorts." (PMID 37463926, 2023). "Specifically, neural signal norepinephrine potentiates the stemness of proximal cancer cells by activating cAMP-CRE axis, where ATF1 serves as a conserved hub." (PMID 37463926, 2023). "Survival analyses in individual cancer cohorts verify the poor prognosis in patients co-expressing nuclear and mitochondrial targets of ATF1/CREB1, confirming the clinical relevance of ATF1 coordinated nucleus-mitochondria program." (PMID 37463926, 2023). "Together, the identification of EWSR1-ATF1 and EWSR1-CREB1 fusion underscores the critical role of constitutive CREB1/ATF1-mediated gene transcription in the development of CCSST and other CCS-like cancers that lack effective therapies." (PMID 36041632, 2022).
cancer (continued). "In contrast, the cancer genes HNRNPA1, PPP2RC5, STRAP, DNAJC14, ATF1 showed upregulation in the cell subpopulations GSC and CD133pos./CD15pos. cells and are located in chromosomal regions that had gains in GSC and CD133pos./CD15pos. cells." (PMID 32634135, 2020). "The cancer genes HNRNPA1, PPP2RC5, STRAP, DNAJC14, and ATF1 showed upregulation in GSC and CD133pos./CD15pos. cells and were included in chromosomal regions that showed gains for GSCs and CD133pos./CD15pos.cells." (PMID 32634135, 2020). "Given that cancer cells often recover the original cell properties by inhibition of key oncogenic signals, we also extract genes that increase upon EWS/ATF1 withdrawal in mouse CCS cells (G1297)." (PMID 31488818, 2019). "There is also the possibility that exosomes that include the genes for activating transcription factor 1 (ATF1) and RAS might be used as biomarkers for cancer." (PMID 40305328, 2025). "Indeed, transcription factors binding cAMP responsive element (CRE) motif (ATF1 and CREB1) and CRE-like motif (AP1) are enriched in the oncospheres of multiple cancer types (7/11 and 6/11 of cancer types for ATF1/CREB1 and AP1, respectively)." (PMID 37463926, 2023). "We presumed that high ATF1 expression confers resistance to PARP inhibitors in cancer cells with HRD because of the alteration of non-BRCA1 HR factors, such as BRCA2, in which sufficient ATF1 and intact BRCA1 could stimulate ATF1-mediated transactivation." (PMID 36860287, 2021). "From a therapeutic perspective, the induction of PKA and CREB/ATF1 activation by aspirin and AMPK may be a disadvantage for treating many cancer types." (PMID 33917483, 2021). "Together, these results confirm the establishment of iPSCs that harbor cancer-related genetic abnormalities from mouse CCS cells in the absence of EWS/ATF1 expression." (PMID 31488818, 2019). "Moreover, ssGSEA analysis with transcription factor gene sets in 1019 human cancer cell lines (The Cancer Cell Line Encyclopedia, CCLE dataset) indicates that CRE transcription factor (ATF1 and CREB1) activities are positively correlated with MYC targets, NRF1 targets and stemness scores." (PMID 37463926, 2023). "We next asked why EWS/ATF1 expression fails to induce cancer development in most cell types." (PMID 31488818, 2019). "We hypothesize that several critical drivers of cancer progression that are active in different cancer types may determine the expression of either Enhancer-SFs or Suppressor-SFs, potentially by modulating the activity of CREB and ATF1 activity." (PMID 30940821, 2019).